KRTAP9-9 (keratin associated protein 9-9)
Description:
In the hair cortex, hair keratin intermediate filaments are embedded in an interfilamentous matrix, consisting of hair keratin-associated proteins (KRTAP), which are essential for the formation of a rigid and resistant hair shaft through their extensive disulfide bond cross-linking with abundant cysteine residues of hair keratins. The matrix proteins include the high-sulfur and high-glycine-tyrosine keratins.
Synonyms: KAP9.5; KAP9.9; KRTAP9-5; KRTAP9.9
Tractability: No criterion of Open Targets' tractability assessment is met for any kind of drug.
Gene: Protein-coding gene on chromosome 17 (41,255,384 to 41,256,364, forward strand). Ensembl gene ENSG00000198083.
Pathways (Reactome):
Developmental Biology: Keratinization
Gene Ontology:
Cellular component: cytosol; keratin filament
Genetic constraint (gnomAD): Loss-of-function variants: 12 observed, 13.89 expected, observed/expected ratio (o/e) 0.86, 90% interval 0.55 to 1.4. The upper end of that interval is the gene's LOEUF score, 1.4, which puts it in group 5 of 6, group 1 being the genes least tolerant of losing a copy. Missense variants: 194 observed, 202.29 expected, observed/expected ratio (o/e) 0.96, 90% interval 0.85 to 1.08. Synonymous variants: 81 observed, 73.65 expected, observed/expected ratio (o/e) 1.1, 90% interval 0.92 to 1.32.
Homologues: Paralogues in human: KRTAP9-2 (96% identical), KRTAP9-7 (92% identical), KRTAP9-3 (88% identical), KRTAP9-8 (87% identical), KRTAP9-6 (84% identical), KRTAP9-4 (82% identical), KRTAP9-1 (79% identical), KRTAP4-12 (53% identical), KRTAP4-6 (50% identical), KRTAP4-9 (50% identical), KRTAP4-11 (48% identical), KRTAP4-5 (46% identical), and 35 more.